MPO (myeloperoxidase)
Diseases named in the same sentence as MPO in open-access papers (continued):
Sharing a sentence is not in itself a finding about the gene and the disease.
liver dysfunction (5 papers, 2015 to 2024). "In previous studies higher serum levels of MPO were associated with NET formation, severe liver dysfunction, and symptoms of PH." (PMID 38603681, 2024). "NE and MPO correlated with the intensity of inflammation, and NE was related to the severity of liver dysfunction." (PMID 36607987, 2023). "Analysis of correlations of serum A1AT, NE, and MPO concentrations with the scoring systems of the severity of liver dysfunction in patients with ALD (Spearman’s rank correlation)a." (PMID 36607987, 2023). "Comparison of serum A1AT, NE, and MPO concentrations in patients with ALD assigned by liver dysfunction according to the MELD score (Mann-Whitney test)a." (PMID 36607987, 2023). "MPO-DNA could identify patients with liver dysfunction with an AUC of 0.842 (95%CI: 0.719–0.965, p=0.0002, se: 84.2%, sp: 72.7% for the value of 12.89 ng/ml)." (PMID 33240258, 2020).
lymphopenia (5 papers, 2020 to 2025). Reduction in the number of lymphocytes. "Lymphopenia has been reported in the active stage of PR3-AAV, but whether lymphopenia also exists in patients with MPO-AAV remains to be studied." (PMID 34289887, 2021). "As in PR3-AAV, we confirmed the existence of lymphopenia, especially CD4+ T cells in MPO-AAV." (PMID 34289887, 2021). "These include: lymphopenia; neutrophilia; neutrophil activation; increased intermediate and non-classical monocytes; high CD64 expression on monocytes and neutrophils; and raised levels of IL-6, IL-18, PAI-1, sCD25, sTNF-R, IP-10, MPO, and PTX3." (PMID 34632327, 2021).
meningitis (5 papers, 2019 to 2025). A disorder characterized by acute inflammation of the meninges of the brain and/or spinal cord. "We used the following keywords: pachymeningitis, meningitis, dura, antineutrophil cytoplasmic antibody, myeloperoxidase, and proteinase-3." (PMID 36188377, 2022). "An experimental study in neonate rats with induced Streptococcus agalactiae meningitis showed a remarkable MPO activity from 24 to 96 h in the hippocampus and from 6 to 96 h in the cortex." (PMID 31581487, 2019). "Shotgun proteomic analysis of the CSF from patients with meningitis confirmed the presence of NET-related proteins, such as MPO, NE, proteinase-3 (PR3), cathelicidin LL-37, MMP-9, heparin binding protein (HBP), neutrophil gelatinase-associated lipocalin (NGAL), and histones." (PMID 31766346, 2019).
Microscopic hematuria (5 papers, 2012 to 2023). Microscopic hematuria detected by dipstick or microscopic examination of the urine. "Based on the results for microscopic hematuria and positive serum myeloperoxidase (MPO)-ANCA, she was strongly suspected as AAV." (PMID 37900606, 2023). "A 69-year-old male had initially presented with low-grade proteinuria, microhematuria, and a positive myeloperoxidase anti-neutrophilic antibody (ANCA)." (PMID 26301224, 2015). "Our patient presented with a clinical picture of RPGN, with a high serum titer of MPO-ANCA preceded by seven years of proteinuria and microscopic hematuria with mildly compromised but stable renal function." (PMID 22656245, 2012). "Detection of MPO-ANCA with alveolar hemorrhage and microhematuria supports the presence of alveolar and glomerular vasculitis as Bosch has suggested." (PMID 22958435, 2012).
Myocardial fibrosis (5 papers, 2019 to 2025). "Elevated levels of myeloperoxidase (MPO), an oxidative stress biomarker, have been correlated with increased myocardial fibrosis and microvascular thrombosis in trauma patients." (PMID 40710793, 2025). "n-3 fatty acid supplementation was also associated with significant decreases in the levels of myeloperoxidase and lipoprotein-associated PLA2 as well as the suppression of tumorigenicity 2 (ST2), a marker of myocardial fibrosis." (PMID 38248822, 2023).
oral mucositis (5 papers, 2019 to 2023). Inflammation of the mucous membranes of any of the structures in the mouth. "The level of MPO activity increased overall during the course of oral mucositis." (PMID 36499758, 2022). "Furthermore, patients who developed oral mucositis presented lower myeloperoxidase and peroxidase concentration than those without oral mucositis." (PMID 35456122, 2022).
osteomyelitis (5 papers, 2018 to 2025). An acute or chronic inflammation of the bone and its structures due to infection with pyogenic bacteria. "Current research indicates that MPO contributes to the pathogenesis of osteomyelitis not only through its antimicrobial activity but also by exacerbating local inflammatory responses via the production of oxidative products." (PMID 41278027, 2025). "Additionally, elevated MPO levels in osteomyelitis patients have been found to correlate with disease severity." (PMID 41278027, 2025). "Further experiments could be conducted to explore the mechanisms of chronic osteomyelitis formation by regulating MPO and PRTN3." (PMID 41278027, 2025). "In chronic osteomyelitis, sustained MPO activity may result in a prolonged inflammatory state, hindering bone tissue repair, and ultimately leading to persistent tissue destruction and functional loss." (PMID 41278027, 2025). "First, high numbers of neutrophils accumulated at the site of osteomyelitis are lysed by PVL, causing them to release substances such as HNPs or myeloperoxidase, which then in a second step strongly activate platelets, both directly and through formation of FDP-lysine presenting proteins." (PMID 29391581, 2018). "Additionally, current literature suggests that a sustained inflammatory response involving MPO and PRTN3 may contribute to the transition from acute to chronic osteomyelitis." (PMID 41278027, 2025).
otitis media (5 papers, 2015 to 2024). Inflammation of the anatomical structures of the middle ear, which is most often caused by an infectious process. "MPO-ANCA shows predominantly OME-type otitis media and a higher incidence of otitis media." (PMID 39124565, 2024). "On the contrary, retrospective multi-center study of Japanese patients with GPA or MPA showed that MPO-ANCA positive cases tended to have ear involvement more frequently, reflected in the fact that otitis media was significantly higher than in PR3-ANCA positive cases." (PMID 26223225, 2015). "Although myeloperoxidase and proteinase 3 anti-neutrophil cytoplasmic antibodies (MPO-ANCA, PR3-ANCA) were negative in the blood examination, otitis media with ANCA-associated vasculitis was suspected, and prednisolone (30 mg/day) was orally administered without antibiotics." (PMID 31918670, 2020).
Peptic ulcer (5 papers, 2015 to 2025). The term peptic ulcer refers to acid peptic injury of the digestive tract, resulting in mucosal break reaching the submucosa. "The enzyme myeloperoxidase (MPO) has been reported with a marker infiltration of neutrophils in inflamed tissue, increasing their activity in several studies have been associated with the presence of peptic ulcer." (PMID 26244547, 2015). "Flavonoids, such as quercetin, quercitrin and afzelin, genistein, aromadendrin-4′-O-methyl-ether and kaempferide, kaempferol, and rutin, have been shown to decrease MPO levels, thereby exhibiting anti-inflammatory activity in peptic ulcer." (PMID 33050668, 2020). "In the development of peptic ulcer, recruitment of neutrophils and other inflammatory cells to the damaged sites activates secreted enzyme MPO, which promotes oxidative stress." (PMID 33050668, 2020). "Flavonoids ameliorate inflammatory symptoms in peptic ulcer by regulating myeloperoxidase (MPO), nitric oxide synthase (NOS), inflammatory signaling pathways, and inflammatory cytokines." (PMID 33050668, 2020). "Previously published studies also demonstrated that the administration of β-myrcene could prevent increased MPO activity in a rat model of ethanol-induced peptic ulcer and in acetaminophen-induced hepatotoxicity." (PMID 36557879, 2022).
pneumococcal infection (5 papers, 2010 to 2023). Infections with bacteria of the species streptococcus pneumoniae. "Following pneumococcal infection, Csf3r−/− mice presented lower levels of myeloperoxidase (MPO), a marker of neutrophil recruitment, in lung homogenates at 36 hr post-infection." (PMID 37222419, 2023). "During pneumococcal infection, spleens from Puma−/− mice demonstrated greater density of neutrophils when compared to those from Puma+/+ animals as confirmed by staining for myeloperoxidase and neutrophil 7/4 antigen." (PMID 21203486, 2010). "In addition, a high observed 3Cl-Tyr/p-Tyr ratio indicates MPO activation and could serve as a biomarker for grading the severity of inflammation and, orientate the clinician towards a pneumococcal infection." (PMID 31581487, 2019).
sarcoma (5 papers, 2015 to 2025). A usually aggressive malignant neoplasm of the soft tissue or bone. "Therefore, MET amplification may have promoted the recruitment of MPO-deficient neutrophils in the microenvironment of the mediastinal sarcoma." (PMID 39421445, 2024). "Histiocytic sarcoma cells are derived from bone marrow monocyte precursors, expresses monocyte-macrophage antigens (CD163, CD68, and lysozyme) and lack expression of myeloid antigens such as CD33, CD13 and MPO." (PMID 29463311, 2018).
acute appendicitis (4 papers, 2016 to 2024). "The number of neutrophils and the levels of H2O2 and MPO were obviously elevated in the microenvironment of acute appendicitis." (PMID 39225387, 2024). "More specifically, cfDNA, MPO, NE, and H3cit were significantly elevated in mice and humans with appendicitis compared to controls." (PMID 33106536, 2020). "However, Swedish authors have reported that among new inflammatory markers, serum amyloid A (SAA), matrix metalloproteinase (MMP-9), and myeloperoxidase (MPO) were the strongest discriminators of all cases of appendicitis." (PMID 37509519, 2023). "The current study suggests that markers of neutrophil activation and extracellular trap formation like cfDNA, NE, MPO, and H3cit may be excellent predictors of appendicitis." (PMID 33106536, 2020). "Serum delta neutrophil index (DNI) and myeloperoxidase index (MPXI) are new inflammatory markers, and thus, in the present study, the authors evaluated the predictive values of these two markers for the presence of a complication in children with acute appendicitis." (PMID 26859663, 2016).
antiphospholipid syndrome (4 papers, 2023 to 2026). A disorder caused by the presence of autoantibodies directed against phospholipids, causing a hypercoaguable state, which may result in blood clots, stroke, heart attack, and in women, significant pregnancy-related complications, including miscarriage and still birth. "Recent studies have shown that specific markers of NETs, such as Cit-H3 and MPO in peripheral blood, can predict VTE events in patients with malignant tumors, novel coronavirus infection, and antiphospholipid syndrome." (PMID 41445740, 2025). "Notably, evidence has demonstrated that antiphospholipid antibodies (aPLs) and anti-β2GPI antibodies isolated from patients with antiphospholipid syndrome (APS) can induce human neutrophils to release NETs as well as massive expressions of ROS, Cit-H3, and myeloperoxidase (MPO)." (PMID 39337405, 2024).
autism (4 papers, 2022 to 2025). Persistent deficits in social interaction and communication and interaction as well as a markedly restricted repertoire of activity and interest as well as repetitive patterns of behavior. "It was reported that serum IMA levels were higher in patients with autism compared to controls, and there was a significant positive correlation between IMA levels and myeloperoxidase." (PMID 38995319, 2024). "The fivefold downregulated MPO, TMCC3, MMP8, CA1, and ELF3 genes and the fivefold upregulated MTRNR2L8 gene can be considered for the early identification of autism patients among Saudis." (PMID 35215271, 2022). "Camel milk is reported to be a useful CAM support for autistic children, as it may increase superoxide dismutase (SOD) and myeloperoxidase (MPO), and lower levels of oxidative stress, which is a suggested factor in the aetiology of autism." (PMID 38972931, 2025).
B-cell lymphoma (4 papers, 2012 to 2025). "A biopsy of the right mammary gland tumor was performed, showing CD20 (+), CD21 (-), bcl-2 (+), CD10 (+), CD30(-), bcl-6 (+), MUM-1 (+), C-myc (70%+), CD19 (+), TDT (-), MPO (-), Ki-67 (+90%), MYC, and BLC2 rearrangements; a pathological diagnosis of high-grade, double-hit B-cell lymphoma was made." (PMID 36032118, 2022).
bacterial pneumonia (4 papers, 2011 to 2024). Acute infection of the lung parenchyma caused by bacteria (e.g., Streptococcus pneumoniae, Haemophilus influenzae, Chlamydia pneumoniae, Mycoplasma pneumoniae, and Legionella pneumophila). "For example, LTF, MPO, LCN2, and S100A9 are markers of neutrophil degranulation previously associated with bacterial pneumonia." (PMID 39409176, 2024). "Patients with bacterial pneumonia had neutrophils with increased markers of activation and a defective respiratory burst, with airway fluid containing higher MPO and NE activity and decreased killing of H. influenzae and S. aureus." (PMID 35913450, 2022). "NET formation was dependent on neutrophil elastase and myeloperoxidase in a mouse model of bacterial pneumonia." (PMID 22163282, 2011). "Notably, although the inhibition of NE and MPO may be beneficial in limiting tissue destruction during the inflammatory process in the lungs during bacterial pneumonia, this may also be a limiting factor given that NE and MPO also mediate bacterial killing." (PMID 34777376, 2021).
cardiac arrest (4 papers, 2010 to 2023). Cessation of breathing and/or cardiac function. "Elevated ICU admission levels of OPN and MPO predicted disturbances in cEEG during the subsequent 48 h after cardiac arrest." (PMID 36053856, 2023). "An experimental cardiac arrest of long duration results in significant alteration of cerebral oxidative injury as indicated by analyses of malonialdehyde, myeloperoxidase, leucigenin, luminol, and glutathione indicating great harm that does not increase greatly after 5-min untreated cardiac arrest." (PMID 28895060, 2018).
cardiomyopathy (4 papers, 2023 to 2025). A disease of the heart muscle or myocardium proper. "Markers such as MDA and MPO, which have demonstrated prognostic value and are implicated in oxidative stress–induced cardiomyopathy, may serve as actionable targets to evaluate and enhance the impact of interventions aimed at reducing oxidative stress and inflammation." (PMID 41154558, 2025). "Several lipid peroxidation markers (e.g., MDA and MPO) are promising predictors of mortality and play a significant role in OS-induced cardiomyopathy." (PMID 36979896, 2023).
cerebral aneurysm (4 papers, 2018 to 2024). "After cerebral aneurysm induction, neutrophil infiltration, pro-inflammatory marker expression, and reduction of α-smooth muscle actin were significantly less in the cerebral arteries of MPO-deficient mice." (PMID 39654759, 2024). "Additionally, in human cerebral aneurysm samples, MPO has been shown to be associated with a neutrophil inflammatory cell infiltrate, degenerative remodeling of the arterial wall, and wall rupture." (PMID 33081376, 2020). "The results of μMRI of MPO activity associated with aneurysmal pathology and immunohistochemistry demonstrated active involvement of neutrophils and neutrophil NETs as a result of pro-inflammatory signalling in the vascular wall and in the perivascular space of brain aneurysms." (PMID 29769642, 2018). "We observed the presence of intracellular and extracellular neutrophil MPO antigen in the majority of samples of clipped brain aneurysms." (PMID 29769642, 2018). "Here we report the utility of μMRI for detecting MPO activity in inflammatory lesions within the vascular wall of excised human brain aneurysms (hBA) and arteriovenous malformations (AVM)." (PMID 29769642, 2018). "Increased MPO expression has been demonstrated within locally sampled plasma and within the walls of human cerebral aneurysms, and reduced MPO expression was found to correlate with decreased cerebral aneurysm formation and rupture in an MPO-knockout mouse model." (PMID 33081376, 2020).
cholestasis (4 papers, 2013 to 2024). Impairment of the bile flow caused by obstruction within the liver, or outside the liver in the bile duct system. "VE administered to ANIT-treated rats prevented liver cell damage, but not cholestasis, and attenuated increased serum lipid peroxide level, increased hepatic lipid peroxide level and myeloperoxidase activity, and decreased hepatic superoxide dismutase activity." (PMID 23710219, 2013).
cholesteatoma (4 papers, 2013 to 2025). A pathologic process characterized by the proliferation of keratinizing squamous epithelium resulting in the accumulation of keratin and cells in the middle ear and/or mastoid. "Serum MPO, MDA, 4-HNE, and NO levels were also higher, and TAC levels lower, in COM patients with compared to those without cholesteatoma, although none of these differences was statistically significant (p > 0.05)." (PMID 39857337, 2024). "Serum MPO activity and MDA, 4-HNE, and NO levels were significantly higher in patients with cholesteatoma than in those without, but the difference between groups was not statistically significant (for all, p > 0.05)." (PMID 23756625, 2013). "In the patients with cholesteatoma, serum MPO activity and levels of MDA, 4-HNE, and NO were significantly higher, and TAC levels were significantly lower than in the patients without cholesteatoma, though the differences between the groups were not statistically significant." (PMID 40227356, 2025). "In addition, serum MPO activity, MDA, 4-HNE, and NO levels were significantly higher in patients with cholesteatoma than in those without, while TAC levels were significantly lower; but the difference between groups was not statistically significant." (PMID 23756625, 2013). "Serum MPO activity and MDA, 4-HNE and NO levels were significantly higher in patients with cholesteatoma than in those without cholesteatoma, while TAC levels were significantly lower; but the difference between groups was not statistically significant (p > 0.05)." (PMID 23756625, 2013).
chorioamnionitis (4 papers, 2009 to 2020). A morphologic finding indicating inflammation of the fetal sac membranes. "In our study, 6 out of 39 PT infants (15.4%) were born to chorioamnionitis diagnosed mothers, 3 of them presenting above average MPO and calprotectin values for this group." (PMID 33537270, 2020). "However, 14d after endotoxin administration preterm animals had increased numbers of T-lymphocytes, myeloperoxidase-positive cells and gammadelta T-cells which lasted till 30d after induction of chorioamnionitis in then near term animals." (PMID 19503810, 2009). "Neutrophilic chorioamnionitis was common in the BSCI and GBS groups, but was more severe in the BSCI+GBS group with greater myeloperoxidase staining (granulocyte marker) in the amnion and chorion (p < 0.05 vs. GBS)." (PMID 32425945, 2020).
coagulation disorders (4 papers, 2020 to 2025). "TF level was also positively correlated with TNF-α, IL-1β, IL-6, and MPO levels and was negatively correlated with IL-10, indicating that the TF level was closely associated with the inflammatory factors, which may cause coagulation disorders." (PMID 32587471, 2020).